MIR551A (microRNA 551a)
Synonyms: hsa-mir-551a; MIRN551A; mir-551a
Gene: MicroRNA gene on chromosome 1 (3,560,695 to 3,560,790, reverse strand). Ensembl gene ENSG00000207776.
Gene Ontology:
Biological process: miRNA-mediated post-transcriptional gene silencing
Cellular component: RISC complex